RAVER2 (ribonucleoprotein, PTB binding 2)
Description:
May bind single-stranded nucleic acids.
Synonyms: KIAA1579; FLJ10770
Tractability: PROTAC: ubiquitination databases record sites on it.
Gene: Protein-coding gene on chromosome 1 (64,744,861 to 64,833,233, forward strand). Ensembl gene ENSG00000162437.
Subcellular location: Nucleus; Cytoplasm
Subcellular location (Human Protein Atlas): Nucleoplasm
Gene Ontology:
Molecular function: RNA binding; nucleic acid binding
Cellular component: cytoplasm; nucleus
Genetic constraint (gnomAD): Loss-of-function variants: 35 observed, 56.91 expected, observed/expected ratio (o/e) 0.62, 90% interval 0.47 to 0.81. The upper end of that interval is the gene's LOEUF score, 0.81, which puts it in group 3 of 6, group 1 being the genes least tolerant of losing a copy. Missense variants: 691 observed, 718.61 expected, observed/expected ratio (o/e) 0.96, 90% interval 0.9 to 1.02. Synonymous variants: 278 observed, 264.69 expected, observed/expected ratio (o/e) 1.05, 90% interval 0.95 to 1.16.
Homologues: Orthologues: chimpanzee RAVER2 (97% identical), macaque RAVER2 (96% identical), dog RAVER2 (90% identical), pig RAVER2 (88% identical), mouse Raver2 (79% identical), rabbit RAVER2 (78% identical), rat Raver2 (72% identical), guinea pig RAVER2 (59% identical), tropical clawed frog raver2 (49% identical), zebrafish raver2 (47% identical), Drosophila melanogaster nito (10% identical), Drosophila melanogaster nonA (8% identical), and 1 more. Paralogues in human: RAVER1 (40% identical), SPEN (20% identical), PSPC1 (11% identical), SFPQ (11% identical), RBM15B (11% identical), NONO (10% identical), RBM15 (10% identical).
Diseases named in the same sentence as RAVER2 in open-access papers:
RAVER2 is named in the same sentence as 5 diseases in open-access papers, as found by Europe PMC text mining. Sharing a sentence is not in itself a finding about the gene and the disease. The quoted sentences say what the papers report.
ischaemic stroke (1 paper, 2023). "Similarly, other annotated mRNAs identified in the current study have been previously associated with a range of indications including liver injury (RAVER2,) and intestinal disease (MYO5B,), but have not been directly associated with ischaemic stroke diagnosis." (PMID 38007520, 2023).
RAVER2 also shares sentences with these, for which no sentence is quoted: glioma (1 paper); intestinal disease (1); myelodysplastic syndrome (1); neurodegenerative disease (1).